INS (insulin)
Diseases named in the same sentence as INS in open-access papers (continued):
Sharing a sentence is not in itself a finding about the gene and the disease.
Obesity (continued). "These two cytokines contribute to the decreased insulin sensitivity observed in obesity." (PMID 37112628, 2023). "Thus, while the carbohydrate–insulin model remains an important mechanism for driving obesity the conversion of fructose has an important role in how high glycaemic carbohydrates cause obesity." (PMID 37482773, 2023). "Despite the fact that insulin resistance emerges to be partially independent of fat, still the worsening of the resistance to insulin in PCOS is apparently the work of obesity, due to which it results in compensatory hyperinsulinemia that contributes to hyperandrogenemia in a variety of ways." (PMID 37854752, 2023). "While obesity leads to imbalances in the circulating levels of peptides such as leptin, insulin, and ghrelin which can decrease or increase olfactory sensitivity, a compromised sense of smell can instead affect body weight by acting on the control mechanisms of eating behavior." (PMID 36837824, 2023). "Disturbances in M1 and M2 levels affect insulin sensitivity in obesity." (PMID 37371961, 2023). "Obesity and insulin are factorsthat raise the iron level in PCOS patients, which iron-oxidativestress governs the function of ovarian tissue,also ferritin and transferrin increases in obese PCOSpatients with inverse correlation between ferritin andthe of the ovaries size." (PMID 37790203, 2023). "Although both DCs and Th cell subsets in metabolic tissues have been associated with control of metabolic homeostasis, little is known about the regulation of DC-mediated Th cell polarization in these organs during the development of obesity or its impact on whole-body insulin sensitivity." (PMID 37140993, 2023). "Attenuation of elevated insulin levels appears to be beneficial with preserved beta-cell function in isolated islets and improvement in triglycerides and 2 h glucose in children with obesity." (PMID 37623862, 2023). "The interventional impairment of olfactory sensory perception using a specific intranasal device resulted in a reduction in body weight, improved insulin sensitivity, and decreased preferences for sweet foods in subjects aged ≤ 50 years with obesity on a low-calorie diet compared to a control group." (PMID 38248819, 2023). "In addition, quercetin improves skeletal muscle mitochondrial function and improves insulin sensitivity in animal models for diet-induced obesity." (PMID 37371902, 2023). "Limitations of the study include the fact that measurements of plasma insulin, cortisol, melatonin, and leptin could have elucidated some information on the variations of the prevalence of obesity in both girls and boys." (PMID 37508610, 2023). "For example, daily ingestion of Akkermansia muciniphila for three months was recently shown to improve indices of metabolic health (insulin sensitivity, plasma lipid profile and fat mass) in individuals living with overweight or obesity during a randomised, double-blind, placebo-controlled trial." (PMID 37402955, 2023). "Our findings indicate that the reduction of serum BCAA concentrations following SG is associated with improved insulin sensitivity, and consistent with prior studies demonstrating a correlation between higher BCAA concentrations and IR in individuals with obesity." (PMID 37686833, 2023). "Consequently, currently, there are no approved PTP1B inhibitors, despite the high demand for the effective treatment of the diseases associated with insulin and leptin resistance (T2DM, metabolic syndrome, and obesity)." (PMID 36901928, 2023). "This metabolically activated phenotype is induced by saturated fatty acids released by insulin-resistant fat cells in obesity that are not only in fat but also in mammary fat and in other tissues, and secrete proinflammatory cytokines involved in tumorigenesis." (PMID 36674935, 2023). "Importantly, adipose tissue becomes dysfunctional in obesity, promoting a pro-inflammatory, dyslipidemic and insulin-resistant environment that enhances T2DM." (PMID 38049873, 2023).
Obesity (continued). "One of the best-proven hypotheses is the chronic inflammatory mechanism in people with obesity that interferes with insulin signaling, or IR processes." (PMID 36839169, 2023). "However, the transition from phase 1b up to phase 3 in the PWS group was accompanied by significant increases in insulin, coinciding in weight gains, obesity, and hyperphagia." (PMID 37546289, 2023). "Thus, finding an association between dietary changes and AN, after adjusting for the presence of obesity, suggests a shift in insulin resistance which, however, requires confirmation with biochemical measures." (PMID 37375623, 2023). "Furthermore, an increased level of PA, a saturated fatty acid, impairs autophagy and insulin signaling in neurons in obesity." (PMID 37047207, 2023). "By exposing human first-trimester trophoblasts to obesity-related plasma factors, we demonstrate that insulin has a direct effect on the regulation of ID2 levels, suggesting that the adverse effects of maternal obesity on preeclampsia begin at an early stage of placental development." (PMID 36768469, 2023). "However, a recent meta-analysis illustrated that clinical use of TZT for 1 year in the management of obesity and glucose control was superior compared to semaglutide, dulaglutide, degludec, and insulin." (PMID 37208555, 2023). "Obesity-related factors, such as immunity, insulin, adiponectin, adipocytokines and nonalcoholic fatty liver and inflammatory reaction may affect the occurrence of obesity and increase the risk of cancer." (PMID 36836694, 2023). "ER stress can be elicited by saturated fats, VLDL production, insulin and obesity." (PMID 37267233, 2023). "However, it is known that the action of insulin in obesity must be comprehended considering its pleiotropic actions in multiple organs, mainly driven by factors that are independent of carbohydrate intake." (PMID 37296485, 2023). "Of note, acute leptin reduction after hyperleptinemia in the context of obesity exhibited a beneficial effect on obesity and insulin sensitivity, indicating that manipulation of circulating leptin level may provide a therapeutic strategy." (PMID 37547309, 2023). "β-cell function is an understudied T2D risk factor in relation to obesity-related pro- and anti-inflammatory mediators, unlike insulin sensitivity, thereby representing another strength of this study." (PMID 37299403, 2023). "Recent studies have demonstrated that shorter sleep durations can promote peptide release and inhibit leptin release, leading to increased food intake, weight gain, decreased insulin sensitivity, and elevated blood glucose levels, ultimately contributing to obesity and impaired glucose tolerance." (PMID 37388641, 2023). "Excess lipids are not only detrimental to the action of insulin but also contribute to a wide range of obesity comorbidities for which macrophage GR therefore may have an unexpected protective function and warrants further investigation." (PMID 37080971, 2023). "These lipids interfere with the insulin signaling pathway and represent one of the key aspects that could contribute to the metabolic imbalance that leads to obesity and the onset of related diseases." (PMID 37371902, 2023). "Within this tangled crosstalk of intertwined processes, miRNAs are recognized to be directly involved in regulating insulin signaling and glucose metabolism at different levels, thereby being capable of promoting either insulin sensitivity or IR in subjects with obesity." (PMID 37672200, 2023). "Therefore, in the case of unhealthy obesity, fat mobilization from adipocytes is impaired, and insulin is incapable of suppressing lipolysis." (PMID 37371902, 2023). "In the present study, we can suggest that the significantly decreased adiponectin level in the MS group may deteriorate the insulin sensitivity, lipid profile, obesity markers, and TNF-α reactivity." (PMID 36991247, 2023).
Obesity (continued). "Indeed, to induce an insulin-sensitive obesity phenotype in mice, we had performed parallel repeated induction experiments in multiple batches of mice." (PMID 37884540, 2023). "Dietary phloretin reduced plasma glucose concentrations, AGEs formation, and insulin levels in a high-fat diet-induced obesity mouse model and improved fasting blood glucose levels, glucose tolerance, and insulin sensitivity in type 2 diabetic rats to a similar degree as metformin treatment." (PMID 35771396, 2023). "We subsequently analyzed publicly available transcriptomic data from VAT of individuals with obesity (GSE20950) who are insulin sensitive (IS) or insulin resistant (IR), to test if there is a further decline of SLC2A4 expression in the combined obese and insulin resistant state." (PMID 37047391, 2023). "Several studies have reported that acupuncture may improve insulin sensitivity and is effective against metabolic disturbances including obesity." (PMID 37729132, 2023). "Due to obesity and IR, there are alterations in the levels of amino acids in the plasma in the early stage of lifestyle-related diseases, but fortunately these alterations can be reversed by interventions that improve insulin sensitivity." (PMID 37569834, 2023). "Some studies have indicated that HDL promotes pancreatic beta‐cell insulin secretion as well as modulating glucose uptake in peripheral tissues, thereby explaining the association between HDL, IR and obesity, including the obesity commonly present in women with PCOS." (PMID 37181037, 2023). "While the underlying mechanisms between obesity and cancer are still unknown, obesity disrupts the role of adipocytes in energy homeostasis, and the alteration of adipokine, insulin and sex steroid signaling." (PMID 36680768, 2023). "We also found that BAC improved immune dysfunction, promoted the growth of Akkermansia by utilizing metabolites from mucin degradation, increased serum insulin levels, and prevented obesity by promoting the catabolism of circulating branched-chain amino acids in the brown adipose tissue." (PMID 38203609, 2023). "Additionally, emerging evidence suggests that both SP1 and STAT3 can suppress the expression of pivotal genes implicated in adipocyte differentiation, including PPARγ, C/EBPα, and FABP4, thereby potentially restoring insulin sensitivity and mitigating obesity." (PMID 37445596, 2023). "The adipose cell produces several types of cytokines known as adipokines which influence endocrine signaling pathways such as regulation of insulin signaling in various tissues in the body and may thus provide a molecular link between obesity and T2DM." (PMID 37706122, 2023). "Therefore, instead of a slowing eating pace, strategies of different aspects are needed to improve postprandial blood glucose and insulin responses for preventing obesity and T2DM." (PMID 36904173, 2023). "Muscles play an important role in energy homeostasis, and they may be involved in the pathogenesis of obesity due to their impact on insulin resistance, energy expenditure, and systemic inflammation." (PMID 37374197, 2023). "With GR in macrophages being predicted as a major regulator of obesity-associated gene signatures on the one side and having established its macrophage-mediated insulin-sensitizing action during obesity, we wanted to determine the transcriptional effects of GR ablation in ATMs of obese mice." (PMID 37080971, 2023). "Moreover, FTO inhibitors have been demonstrated to improve insulin sensitivity in high fat diets (HFDs) induced obesity." (PMID 37404756, 2023). "Moreover, individuals with obesity and MetS had higher levels of serum total cholesterol (TC), triglyceride (TG), insulin, and iron (P < 0.05)." (PMID 37670399, 2023).
Obesity (continued). "The body weight, lipid contents, and glucose levels were tested in high-fat diet (HFD)-induced obesity C57BL/6J mice with L. reuteri supplementation to confirm that these anti-obesity and insulin reduction effects of L. reuteri are conserved to mammals under a high-energy diet." (PMID 37163439, 2023). "A possible explanation is that overall and abdominal obesity had different effects on the pathogenesis of T2DM, and overall obesity may affect insulin secretion while abdominal obesity results in worse insulin sensitivity." (PMID 37510476, 2023). "It is known for its anti-obesity capability and insulin sensitization in adipocytes." (PMID 37512578, 2023). "It is also suggested that increased irisin in obesity may be to overcome insulin and irisin resistance, similar to well-documented leptin resistance in obesity." (PMID 38333723, 2023). "In addition, neuronal pathways can influence insulin sensitivity and contribute to the symptoms of insulin resistance syndrome in people with T2D and obesity." (PMID 36808568, 2023). "It has been proposed that glucagon increases with the onset of obesity and fatty liver as a consequence of hepatic glucagon resistance and with insulin resistance due to the inappropriate regulation of glucagon by fasting and a static glucagon/insulin ratio." (PMID 37764697, 2023). "This will help relieve obesity and blood sugar and improve insulin sensitivity." (PMID 38020719, 2023). "What factors might have increased the insulin-to-glucagon ratio on a population basis, concomitant with the obesity epidemic?" (PMID 37661740, 2023). "Formerly, several physiological roles of organokines, including adipokines, hepatokines, myokines and gut hormones have been described in obesity, especially in the regulation of glucose and lipid metabolism, insulin sensitivity, oxidative stress, and low-grade inflammation." (PMID 36837889, 2023). "Consistently, the reduction of B cells in obesity culminates in enhanced insulin sensitivit." (PMID 37957462, 2023). "In addition to TIMP2 deficiency-induced neuromotor deficit and defective myogenesis, TIMP2−/−, both male and female, mice exhibit obesity with a relatively preserved glucose tolerance and insulin sensitivity." (PMID 37445827, 2023). "Interestingly, PRDX2 was upregulated in both insulin-sensitive and insulin-resistant patients, suggesting obesity as a major driver of PRDX2 upregulation." (PMID 37414931, 2023). "One recent evidence indicated that 8 weeks of high-intensity interval cycling substantially elevated the glucose-insulin cycle and metabolic endotoxicity (1 session to 18 sessions equivalent to 24 sessions) in women (aged 18–30 years) with severe obesity (body fat>40%)." (PMID 37608837, 2023). "In summary, we investigated for the first time the differences in circulating metal species among distinct IR phenotypic subtypes among children and adolescents with obesity, who were stratified according to the insulin secretion pattern in response to an OGTT." (PMID 37242230, 2023). "In individuals with obesity, adipose tissue lipolysis intensifies, leading to the release of substantial amounts of free fatty acids, which represents a crucial factor influencing insulin sensitivity modulation." (PMID 37716947, 2023). "Culture with high levels of insulin inhibited Treg-derived IL-10, and impaired the ability of Tregs to exert cytokine mediated immune suppression, potentially explaining reduced Treg function in obesity." (PMID 36992811, 2023). "Our findings suggest a minor role of systemic PRL in pathogenesis of RA and periodontitis as serum levels could be influenced by a variety of factors like obesity and plasma insulin levels." (PMID 36717425, 2023). "The body of literature highlighted here demonstrates that NF-κB signalling not only regulates inflammation during obesity but it is directly linked to energy expenditure by regulation of AMPK and glucose uptake/proliferation by regulation of insulin signalling." (PMID 36175539, 2023).
Obesity (continued). "Concordantly, E. coli LPS levels are elevated in plasma during obesity, characterizing an endotoxemia, and may exacerbate inflammation and insulin resistance in adipose tissue." (PMID 38136564, 2023). "The importance of diet has been described in earlier studies, where obesity was not viewed to be as detrimental as the diet itself: mares fed a high energy diet returned to a normal insulin response despite the persistence of obesity, when the energy intake was reduced to normal." (PMID 37152686, 2023). "Although a significant association between BMI, an indicator of obesity, and the risk of NAFLD has now been found in a large number of observational studies, BMI as a proxy measure of general obesity cannot explain the specific role of obesity on insulin sensitivity." (PMID 36742435, 2023). "It has been demonstrated that APN may enhance insulin sensitivity and protect against obesity, type 2 diabetes, and atherosclerosis." (PMID 37764380, 2023). "Importantly, this study defined for the first time the molecular mechanism of the observed anti-obesity and insulin-sensitizing effects of trodusquemine, which were shown to result from the potent and selective inhibition of PTP1B." (PMID 37298571, 2023). "Thus, this cross-sectional study aimed to investigate the relationship between adherence to MD and IR, insulin sensitivity, and IS in individuals with overweight/obesity." (PMID 37960178, 2023). "Only 2 weeks of maximal all-out cycling (3 sessions/week) resulted in a significant decrease in EAT and PAT, along with increased aerobic capacity and insulin sensitivity in men (aged 43–53 years) affected by obesity with defective glucose tolerance (DGT), whereas HIIT appears superior to MICT." (PMID 37608837, 2023). "Moreover, mature βKO mice were resistant to HFD-induced obesity and glucose intolerance by lowering basal insulin secretion and preserving GSIS capacity." (PMID 37188647, 2023). "Interestingly, 3-aminoisobutyrate has been shown to improve insulin sensitivity and protect against high-fat-diet-induced obesity in mice." (PMID 37298406, 2023). "The lack of TLR4 signaling ameliorated the insulin and glucose signaling abnormalities associated with obesity." (PMID 36674680, 2023). "By reducing the steroid hormone ecdysone, we created a new obese-fly model (OBL) that we propose can be used to investigate obesity-related pathways, including insulin resistance, altered fat metabolism, chronic inflammation, immune system dysfunction and cardiac defects." (PMID 37828911, 2023). "In fact, although weight loss in people with obesity typically increases insulin sensitivity, we identified a subgroup of people in whom marked weight loss did not improve insulin-mediated glucose disposal." (PMID 37159276, 2023). "Additionally, targeting inflammation in the adipose tissue or the hypothalamus introduces new possibilities to prevent diet-induced obesity as well as insulin and leptin resistance." (PMID 37957462, 2023). "We investigated if metformin could be used to attenuate insulin secretion from palmitate-treated isolated islets and its implication for children with obesity." (PMID 37623862, 2023). "In addition to attenuation of obesity-induced inflammation and insulin resistence in obese mice, CD36 peptide treatment alleviated obesity-associated kidney or liver damage." (PMID 37980376, 2023). "In addition, insulin signaling pathways, involving a network of tightly connected cascades, also account for an essential role in the obesity progression." (PMID 37762063, 2023). "GIP infusions resulting in plasma concentrations similar to those observed following oral glucose ingestion, stimulate insulin secretion in a glucose-dependent manner with maximal efficacy at higher postprandial glucose levels, however, its effect is blunted in obesity and T2DM." (PMID 37249754, 2023).